PEX19 (peroxisomal biogenesis factor 19)
Description:
Necessary for early peroxisomal biogenesis. Acts both as a cytosolic chaperone and as an import receptor for peroxisomal membrane proteins (PMPs). Binds and stabilizes newly synthesized PMPs in the cytoplasm by interacting with their hydrophobic membrane-spanning domains, and targets them to the peroxisome membrane by binding to the integral membrane protein PEX3.
Synonyms: HK33; PXF; D1S2223E; PMP1; PMPI; PXMP1; PBD12A
Tractability: Small molecule: a structure with a bound ligand is known. PROTAC: ubiquitination databases record sites on it; its protein half-life has been measured.
Gene: Protein-coding gene on chromosome 1 (160,276,807 to 160,286,348, reverse strand). Ensembl gene ENSG00000162735.
Subcellular location: Cytoplasm; Peroxisome membrane
Subcellular location (Human Protein Atlas): Peroxisomes
Pathways (Reactome):
Disease: Dengue Virus-Host Interactions
Protein localization: Class I peroxisomal membrane protein import
Transport of small molecules: ABC transporters in lipid homeostasis
Gene Ontology:
Molecular function: ATPase binding; peroxisome targeting sequence binding; protein binding; protein carrier chaperone
Biological process: establishment of protein localization to peroxisome; negative regulation of lipid binding; peroxisome fission; peroxisome organization; protein folding; protein import into peroxisome membrane; protein stabilization; protein targeting to peroxisome
Cellular component: cytoplasm; cytosol; peroxisomal membrane; peroxisome; protein-containing complex; brush border membrane; membrane
Genetic constraint (gnomAD): Loss-of-function variants: 29 observed, 37.09 expected, observed/expected ratio (o/e) 0.78, 90% interval 0.58 to 1.07. The upper end of that interval is the gene's LOEUF score, 1.07, which puts it in group 4 of 6, group 1 being the genes least tolerant of losing a copy. Missense variants: 396 observed, 388.01 expected, observed/expected ratio (o/e) 1.02, 90% interval 0.94 to 1.11. Synonymous variants: 141 observed, 142.72 expected, observed/expected ratio (o/e) 0.99, 90% interval 0.86 to 1.14.
Gene-disease validity (ClinGen):
ClinGen rates the evidence that PEX19 causes each of these diseases.
peroxisome biogenesis disorder (autosomal recessive): Definitive.
Homologues: Orthologues: chimpanzee PEX19 (100% identical), dog PEX19 (96% identical), rabbit PEX19 (96% identical), guinea pig PEX19 (93% identical), mouse Pex19 (91% identical), rat Pex19 (88% identical), pig PEX19 (79% identical), tropical clawed frog pex19 (70% identical), zebrafish pex19 (54% identical), Drosophila melanogaster Pex19 (29% identical), Caenorhabditis elegans prx-19 (29% identical).
Diseases named in the same sentence as PEX19 in open-access papers:
PEX19 is named in the same sentence as 34 diseases in open-access papers, as found by Europe PMC text mining. Sharing a sentence is not in itself a finding about the gene and the disease. The quoted sentences say what the papers report.
Zellweger syndrome (8 papers, 2016 to 2025). "Farnesylation of Pex19 is critical for its interaction with client proteins, and mutations of human Pex19 unrelated to its CaaX sequence are associated with Zellweger syndrome." (PMID 38818856, 2024). "To address this question, we made use of two other models: Caenorhabditis elegans and, to assess the clinical relevance of our findings, a human skin fibroblast cell line from a Zellweger syndrome patient with a mutation in PEX19 (Δ19T cells, )." (PMID 29920513, 2018). "Like the pex19a-1 pex19b-1 double mutant, embryo lethality has been reported for null alleles of most membrane peroxins in Arabidopsis, and PEX19 mutations in the human peroxisome deficiency disease, Zellweger Syndrome, can result in death in infancy." (PMID 26824478, 2016). "Pex19 loss of function specifically leads to Zellweger syndrome, the severest form of PBDs." (PMID 29920513, 2018). "Indeed, mutations in the PEX3 and the PEX19 genes lead to the most severe form of the peroxisomal biogenesis disorders, the Zellweger syndrome." (PMID 28817674, 2017). "The human orthologs of PEX19 and PEX3, together with other peroxins, are mutated in Zellweger syndrome, a severe cerebro‐hepato‐renal peroxisome biogenesis disorder (Fujiki, Yagita, & Matsuzaki, 2012)." (PMID 31854076, 2020). "Metabolic aberrations that were associated with compromised PEX19 functions, were solely attributed to the absence of peroxisomes, which is also considered the underlying cause for Zellweger Spectrum Disorders." (PMID 35557938, 2022). "Zellweger spectrum disorders (ZSDs), including archetypal Zellweger syndrome, neonatal adrenoleukodystrophy (NALD) and infantile Refsum disease (IRD), are PBDs caused by mutations in peroxin genes (PEX1, PEX2, PEX3, PEX5, PEX6, PEX10, PEX11β, PEX12, PEX13, PEX14, PEX16, PEX19 or PEX26)." (PMID 40949164, 2025). "For this reason, organs and cell types containing high amounts of PEX3 and PEX19 could be more frequently negatively affected by defects of the peroxisomal biogenesis such as occur in diseases of the Zellweger syndrome spectrum and neonatal adrenoleukodystrophy." (PMID 28817674, 2017). "We have previously shown that major hallmarks of Zellweger syndrome are recapitulated in Pex19 mutant flies, like absence of peroxisomes, VLCFA accumulation, mitochondrial abnormalities, and severely decreased viability." (PMID 29920513, 2018).
peroxisome biogenesis disorder (3 papers, 2016 to 2022). "Although mitochondrial alterations and mistargeting of peroxisomal proteins to mitochondria have been observed in peroxisome biogenesis disorders, it remains to be established whether PEX11β mistargeting contributes to the pathophysiology of PEX19-deficiency and related disorders." (PMID 35678336, 2022). "The connected component of peroxisomal disorders expressed in the hypothalamus consists of PEX19, PEX10, PEX6, and PEX7." (PMID 27748412, 2016).
viral infection (2 papers, 2021 to 2022). "This work highlights the multifunctional role of the ISG viperin and its interaction with the peroxisomal protein Pex19 to modulate peroxisomal-dependent innate signaling that ultimately restricts viral infection." (PMID 34108265, 2021). "However, after transient expression of viperin as would typically be seen following a viral infection, it was evident that there was significant colocalization of Pex19 and viperin at the interface of BODIPY-positive LDs." (PMID 34108265, 2021). "Viperin is expressed at high levels early after viral infection in an IFN-independent manner and we propose that the interaction of viperin with Pex19 drives a rapid and enhanced antiviral response from peroxisomes." (PMID 34108265, 2021). "Interestingly, viperin is expressed early following viral infection by both IFN-independent and dependent mechanisms, and we reasoned that the interaction between viperin and Pex19 (and thus the peroxisome) might modulate the innate antiviral response." (PMID 34108265, 2021).
African sleeping sickness (1 paper, 2021). "Given the essentiality of functional glycosomes and the low amino acid sequence identity between TbPex3 and mammalian Pex3 proteins, makes TbPex3 and its interaction with Pex19 an attractive therapeutic target for the treatment of NTDs like African sleeping sickness and American trypanosomiasis." (PMID 34350186, 2021).
astrocytoma (1 paper, 2020). "Additionally, knockdown of ACOX1 or peroxin 19 (PEX19) induces apoptosis and autophagy in neural cells including human neuroblastoma (SK-N-SH) cells and human astrocytoma (U251) cells, and EV71 infection induces neural cell death through attenuating ACOX1 production." (PMID 32434419, 2020).
breast carcinoma (1 paper, 2023). "For the first time, this paper proposes that HNRNPU and PEX19 are related to the prognosis of DCs in cancer, which also provides new possibilities for finding new targets for breast cancer immunotherapy." (PMID 36835467, 2023). "For the first time, this paper puts forward that HNRNPU and PEX19 are related to the prognosis of dendritic cells in cancer, which also provides new possibilities for finding new targets for breast cancer immunotherapy." (PMID 36835467, 2023).
cardiac arrhythmia (1 paper, 2020). Any disturbances of the normal rhythmic beating of the heart or MYOCARDIAL CONTRACTION. "Oenocyte-specific KD of Pex19, the key peroxisomal membrane assembly factor, did not promote cardiac arrhythmia." (PMID 32523050, 2020).
diabetes (1 paper, 2020). "Here, in this study, our data showed that WFDC2 was upregulated in the tubules causing PEX19 expression to decrease in the glomeruli, which provide a new mechanism of how WFDC2 regulates diabetes and DKD." (PMID 33644086, 2020).
diabetic kidney disease (1 paper, 2020). Progressive kidney disorder caused by vascular damage to the glomerular capillaries, in patients with diabetes mellitus. "Secreted protein comparison and verification experiments indicated that WFDC2 from the tubule could downregulate PEX19 mRNA and protein levels at the glomeruli in diabetic kidney disease (DKD)." (PMID 33644086, 2020).
HIV-1 infection (1 paper, 2020). The type species of lentivirus and the etiologic agent of acquired immunodeficiency syndrome (AIDS). "Finally, the fact that neither Vpu expression nor HIV-1 infection affected the levels of NEFAs in PEX19 knockout cells suggests that the Vpu-dependent increase in NEFAs is due to the downregulation of peroxisomes." (PMID 32127461, 2020).
Hydrocephalus (1 paper, 2025). Hydrocephalus is an active distension of the ventricular system of the brain resulting from inadequate passage of CSF from its point of production within the cerebral ventricles to its point of absorption into the systemic circulation. "Mutations in PEX19 have been associated with multisystem involvement, resulting in severe phenotypes, such as hypotonia, hydrocephalus, cardiac anomaly, genital abnormalities, dense bones, abnormal facial features, and early neonatal death." (PMID 39757991, 2025).
hypothyroidism (1 paper, 2021). Abnormally low levels of thyroid hormone. "Given that depletion of endogenous Pex16 itself increased the direct incorporation of PMPs, our results indicate that hypothyroidism probably favors direct incorporation of PMPs to peroxisomes via Pex19, which hinders Pex16 expression." (PMID 34571897, 2021). "Here we found that hypothyroidism increased Pex19 protein expression from day 15 to the end of treatment, which demonstrated its importance in brown adipocyte peroxisomal biogenesis." (PMID 34571897, 2021). "This is supported by the fact that hypothyroidism induced PMP70 protein expression in parallel with Pex19 from day 15 until the end of treatment." (PMID 34571897, 2021).
liver dysfunction (1 paper, 2025). "One of the reported PEX19 cases with an insertion mutation c.763_764insA showed a less severe phenotype with milder biochemical abnormalities and survived for up to 16 months after developing liver dysfunction and renal tubular defects." (PMID 39757991, 2025). "Based on the missense mutation identified in PEX19 gene in our patient, we hypothesized that she might develop other complications such as liver dysfunction and renal defect over time, although her metabolic profile is currently unremarkable and she has mild clinical features." (PMID 39757991, 2025).
lymphoma (1 paper, 2025). A malignant (clonal) proliferation of B- lymphocytes or T- lymphocytes which involves the lymph nodes, bone marrow and/or extranodal sites. "Another investigation uncovered that the proteins PEX3, PEX16, and PEX19 safeguard lymphoma cells by counteracting cell death prompted by the histone deacetylase inhibitor." (PMID 40487257, 2025).
melanoma (1 paper, 2023). A malignant, usually aggressive tumor composed of atypical, neoplastic melanocytes. "In this present study, we showed that compromising peroxisome biogenesis by targeting PEX3 (or PEX19) sensitizes melanoma to MAPK pathway inhibition and overcomes MAPKi resistance, a phenotype that is more robust when UGCG is simultaneously inhibited." (PMID 37616051, 2023).
myoclonic epilepsy (1 paper, 2025). A group of epilepsy syndromes in which myoclonic seizures are a prominent feature. "There are very few reported cases of PEX19 gene mutations and only eight studies have been published, of which four had missense, two nonsense, and two had frameshift mutations diagnosed with developmental disorder, ZS, PBDs, and myoclonic epilepsy." (PMID 39757991, 2025).
prostate carcinoma (1 paper, 2019). A carcinoma that arises from epithelial cells of the prostate gland. "SLC16A7 (also known as monocarboxylate transporter protein 2, MCT2) is mainly located in the peroxisomes of prostate cancer cells and interacts with Pex19 via the peroxidase transport mechanism." (PMID 30328513, 2019).
Seizure (1 paper, 2012). A seizure is an intermittent abnormality of nervous system physiology characterized by a transient occurrence of signs and/or symptoms due to abnormal excessive or synchronous neuronal activity in the brain. "Seizure susceptibility has been linked to mutations in four selected candidate genes; Pex19, Kcnj10, Pigm, and Cabc1." (PMID 22952935, 2012).
thyroid cancer (1 paper, 2017). "In thyroid cancers, the expression of peroxisomal-biogenesis genes PEX7, PEX11B and PEX19 was significantly increased by energy metabolism." (PMID 28582771, 2017).
tuberous sclerosis (1 paper, 2017). Hereditary disease characterized by seizures, intellectual disability, developmental delay, and skin and ocular lesions. "It was recently shown that the overexpression of PEX3 induces ubiquitination-dependent NBR1-mediated pexophagy and that PEX19 associates with the tuberous sclerosis complex, which is part of the signaling cascade downstream of ATM activating pexophagy in the presence of ROS." (PMID 28817674, 2017).
tumor (5 papers, 2007 to 2025). "PCa tumor cells seem to take advantage of the peroxisomal protein transport machinery in order to target MCT2 to this organelle via peroxin 19 (PEX19), potentially ensuring higher rates of β-oxidation and contributing to the maintenance of the redox balance." (PMID 33121137, 2020).
infection (3 papers, 2019 to 2025). The state of being infected such as from the introduction of a foreign agent such as serum, vaccine, antigenic substance or organism. "The loss of multiple PEX proteins was evident at 24-h post-infection; however, by 48-h, the reduction in PEX3, PEX7, PEX11B, PEX13 and PEX19 was much more pronounced." (PMID 31311201, 2019).
PEX19 also shares sentences with these, for which no sentence is quoted: Zellweger spectrum disorders (2 papers); American trypanosomiasis (1); aspergillosis (1); asthma (1); Breast Invasive Carcinoma (1); cancer (1); coccidioidomycosis (1); endometritis (1); kidney damage (1); neuroblastoma (1); neurological diseases (1); Seckel syndrome (1).